TTR (transthyretin)
Diseases named in the same sentence as TTR in open-access papers (continued):
Sharing a sentence is not in itself a finding about the gene and the disease.
thyroid (6 papers, 2013 to 2025). "PFASs possess thyroid-disrupting effects through various mechanisms, such as binding to transthyretin, activating the NA+/K+-dependent transport of I−, binding to the sites of deiodinases, and inducing transcriptional changes in thyroid-regulating genes." (PMID 40241969, 2025). "Two thyroid-related genes, TTR and TSHR, were observed among the top hits." (PMID 41387570, 2025). "Furthermore, we determined the PTM pattern of TTR in serum of patients with thyroid disease by immunoprecipitation and mass spectrometry to evaluate this association in vivo." (PMID 25311081, 2015). "Furthermore, additional thyroid toxicity tests featuring more different, but ideally, well-characterized CP mixtures are needed to clarify the factors that influence the different activity determined in the TTR-TRβ-CALUX© test." (PMID 33555371, 2021).
acute kidney injury (5 papers, 2019 to 2025). Sudden and sustained deterioration of the kidney function characterized by decreased glomerular filtration rate, increased serum creatinine or oliguria. "Some studies have found that TTR might be a potentially valuable target for rhabdomyolysis induction of acute kidney injury (AKI), which suggests that reducing TTR can increase reactive oxygen species production and induce apoptosis." (PMID 35059432, 2021).
Anxiety (5 papers, 2011 to 2025). Intense feelings of nervousness, tension, or panic often arise in response to interpersonal stresses. "Another heat score associated gene, TTR, a carrier of thyroid hormone, is known to influence anxiety, behavioral activity and mental functions." (PMID 21504592, 2011). "Studies with TTR-null (TTR−/−) mice revealed that these animals present reduced signs of depressive-like behavior and increased exploratory activity and anxiety, probably due to increased levels of noradrenaline in the limbic forebrain." (PMID 33212973, 2020). "Interestingly, math anxiety did not significantly correlate with TTR or CDR performance." (PMID 33199798, 2020).
choroid plexus papilloma (5 papers, 2009 to 2020). "Immunohistochemical characteristics of choroid plexus papillomas are positive expressions of both cytokeratin and vimentin, while transthyretin and S-100 protein are expressed in 80% to 90% of choroid plexus carcinomas." (PMID 32756190, 2020). "Initial difficulties in the differentiation of ELSTs from choroid plexus papilloma were aided by the recognition of transthyretin as a site-specific marker for choroid plexus epithelium." (PMID 24991442, 2014). "Transthyretin, a marker for choroid plexus epithelium, was found to show differential expression between choroid plexus papillomas and aggressive papillary tumors of the endolymphatic sac or duct." (PMID 22472343, 2012). "In an analysis of different brain tumors, transthyretin mRNA and protein were not expressed in 23 anaplastic astrocytomas and glioblastomas, being exclusively limited to choroid plexus papillomas." (PMID 23185417, 2012).
chronic heart failure (5 papers, 2018 to 2026). "The Chinese patient had congestive cardiac failure at 72 years old and a sural nerve biopsy identified transthyretin amyloid deposition in epineural blood vessels and connective tissue." (PMID 40725383, 2025).
dysautonomia (5 papers, 2020 to 2025). An acute or chronic disorder, affecting the sympathetic or parasympathetic nervous system. "We found that display peripheral neuropathy and dysautonomia identified on neurological examination was not uncommon in CA-TTR patients carrying the transthyretin V122I (p.Val142Ile) mutation." (PMID 37256072, 2023). "In our study, the most common reason for referring a patient for TTR testing after a lack of response to IVIg was dysautonomia, manifest as orthostatic hypotension, gastrointestinal problems and erectile dysfunction, which is evocative of ATTRv." (PMID 40025610, 2025).
multiple sclerosis (5 papers, 2010 to 2024). A progressive autoimmune disorder affecting the central nervous system resulting in demyelination. "The crystal structures of wild-type TTR and numerous disease-causing mutants have been identified and studied in patients with multiple sclerosis (MS)." (PMID 39065728, 2024). "In particular, the specific oxidative modification of TTR Cys10 residue in the CSF has been found to be associated with demyelinating diseases (multiple sclerosis and acute disseminated encephalomyelitis)." (PMID 35987087, 2022). "In the CSF of multiple sclerosis patients, TTR oxidized forms and anomalous dimers, which are susceptible to dissociation in reducing conditions, were observed and were specifically associated with the disease." (PMID 35987087, 2022). "Transthyretin was already quoted in literature as a molecule associated with neurological disorders like multiple sclerosis, amyloid polyneuropathy and TSEs." (PMID 21044301, 2010). "The multiple modifications of TTR molecules specifically associated with multiple sclerosis may be markers of imbalanced redox conditions in the brain." (PMID 35987087, 2022). "CSF of multiple sclerosis patients was characterized by TTR oligomerization, thus highlighting the importance of analyzing posttranslational modifications of the proteome in the identification of novel biomarkers of the disease." (PMID 35135578, 2022). "Concomitantly, the modified/oxidized and crosslinked TTR molecules may actively contribute to the pathogenesis of multiple sclerosis, either due to the lack of native TTR function or due to the switch of TTR from a protective to a pathological component of the redox vicious cycle." (PMID 35987087, 2022).
prostate carcinoma (5 papers, 2012 to 2026). A carcinoma that arises from epithelial cells of the prostate gland. "Also, overexpression of TTR may be related to enhanced anoikis resistance and metastatic potential of prostate cancer cells." (PMID 37688511, 2023). "It has been reported that TTR can regulate MAPK/ERK signaling pathways to promote drug resistance, proliferation, and metastasis in prostate cancer cells." (PMID 37688511, 2023).
scrapie (5 papers, 2012 to 2018). A fatal disease of the nervous system in sheep and goats, characterized by pruritus, debility, and locomotor incoordination. "Even in prion models TTR levels have been found strongly increased in the cortex of scrapie-infected mice." (PMID 24898206, 2014). "There are only a couple of records of APPs being of significance in scrapie in sheep, serum transthyretin and urinary α-1Antichymotrypsin have been found to discriminate healthy from scrapie infected both at pre-clinical and clinical stage of scrapie." (PMID 22805457, 2012). "TTR expression is reduced during the APR and the protein has been seen to decrease in serum in late stage scrapie in sheep." (PMID 30208891, 2018).
spinal stenosis (5 papers, 2020 to 2024). Narrowing of the spinal canal. "Both thickened ligamentum flavum and increased lumbar spine instability were associated with a greater quantity of TTR amyloid deposits in spinal stenosis patients." (PMID 33419417, 2021).
thyroid cancer (5 papers, 2018 to 2024). "Several studies have linked flame retardant exposure to thyroid cancer and dose-dependent histopathological alterations in the thyroid gland, with some flame retardants competitively binding to transthyretin, a thyroxine (T4) transporter." (PMID 36339157, 2022). "The involvement of TTR in thyroid cancer is consistent with the previously advanced hypothesis of an increased risk of thyroid cancer in the presence of particularly polybrominated diphenyl ethers (PBDEs), metabolites of which compete with thyroid hormones for binding to TTR." (PMID 29504895, 2018). "Based on these findings, we postulate that PM10 decreases the incidence of thyroid cancer through increased thyroid receptor-mediated activity by increasing FT3, which results in decreased TSH levels, initiation of the HPT axis, and induction of hepatic transthyretin." (PMID 34732774, 2021).
uveitis (5 papers, 2018 to 2025). An inflammatory process affecting a part of or the entire uvea. "A significantly higher concentration of transthyretin (TTT) in aqueous humor of patients with silent chronic AU and JIA-associated uveitis as compared to other groups led to its identification as a potential intraocular biomarker of JIA-associated uveitis." (PMID 33343583, 2020). "In a pilot study on three children with JIA-uveitis, elevated levels of proteins associated with inflammatory arthritis (SEMA3G, TIMP1, HEXB, ERN1, and SAA1) was found, in addition to elevated levels of sCD14, S100A8, and SAA1, but reduced levels of S100A9, LAP3, TTR, and MIF." (PMID 34438537, 2021). "However, they also hypothesized that transthyretin expression might be a consequence of this uveitis, serving as a marker for silent chronic non-infectious anterior uveitis." (PMID 41402737, 2025).
diabetic neuropathy (4 papers, 2018 to 2026). A chronic, pathological complication associated with diabetes mellitus, where nerve damages are incurred due to diabetic microvascular injury involving small blood vessels that supply these nerves, resulting in peripheral and/or autonomic nerve dysfunction. "Twenty‐four patients with TTR‐FAP and 48 patients with diabetic polyneuropathy (dPNP) were investigated (neurological impairment score NIS; neurological disability score NDS) in a cross‐sectional design." (PMID 29568686, 2018).
endometrial cancer (4 papers, 2010 to 2024). Primary or metastatic malignant neoplasm involving the endometrium (mucous membrane that lines the endometrial cavity). "Another study suggested that the panel of ApoA-I, TTR, and TF distinguished normal samples from early-stage endometrial cancer with a sensitivity of 71% (specificity, 88%) and normal samples from late stage endometrial cancer with a sensitivity of 82%." (PMID 31035965, 2019). "For plasma proteins, a six-biomarker panel combining SERPINA4, APOA2, TTR, CRP, CLEC3B and APOD predicted advanced stage endometrial cancer with AUC 0.93 (0.85–0.99)." (PMID 38513301, 2024).
ependymoma (4 papers, 2013 to 2019). A WHO grade II, slow growing tumor of children and young adults, usually located intraventricularly. "TTR mRNA or TTR protein have been found in retinal pigmented epithelial cells, leukocytes, pancreatic islets, dorsal root ganglia, ependymoma cells and others." (PMID 27501389, 2016). "This supports previous results showing endocytosis of fluorescence-labeled TTR in ependymoma cells." (PMID 31817149, 2019). "Furthermore, increased uptake of TH in cells treated with both T4 and TTR probably involves a T4 complex with TTR, as well as passive diffusion of T4, allowing for greater cell uptake than can be accomplished by diffusion only, which is consistent with observations in human ependymoma cells." (PMID 31817149, 2019). "TTR receptors have been invoked for the internalization of soluble WT TTR in the context of normal catabolism in hepatocytes, and T4 transport in astrocytoma, chicken oocytes and ependymoma cells, although none has been identified." (PMID 25395306, 2015). "The expression of cytokeratin and transthyretin by tumor cells and the lack of GFAP expression differentiated this tumor from ependymoma, and the co-expression of cytokeratin, S-100 protein and vimentin with negative CEA was helpful in distinguishing it from metastatic carcinoma." (PMID 22752623, 2013).
hemophilia A (4 papers, 2022 to 2025). The most common form of hemophilia characterized by spontaneous or prolonged hemorrhages due to factor VIII deficiency. "The E03.TTR promoter was used in gene therapies for hemophilia A DTX201 (BAY2599023) and Wilson’s disease UX701." (PMID 41511298, 2025). "A human FVa (hFVa) expression cassette was constructed, and AAV8 vectors encoding hFVa (AAV8/TTR-hFVa) were intravenously administrated into mice with hemophilia A and B with or without FVIII inhibitors." (PMID 35991645, 2022). "In this study, we determined the MED of our clinical candidate vector, AAVhu37.E03.TTR.hFVIIIco-SQ.PA75, in a hemophilia A mouse model." (PMID 34652966, 2022). "Results of a second long-term study in hemophilia A dogs treated with AAV-cFVIII delivered in AAV2, AAV6, and AAV8 with the liver-specific transthyretin (TTR) promoter were presented at the roundtable, and in this case also, no transformation was detected in dog liver." (PMID 35690906, 2022). "The present study describes a pharmacology study with safety measurements for our clinical candidate vector, AAVhu37.E03.TTR.hFVIIIco-SQ.PA75, in FVIII KO mice to determine the minimally effective dose (MED) and to support the initiation of a Phase 1 clinical trial in patients with hemophilia A." (PMID 34652966, 2022).
hemophilia B (4 papers, 2020 to 2023). Hemophilia B is a form of hemophilia characterized by spontaneous or prolonged hemorrhages due to factor IX deficiency. "BAX 335 is an AAV8-based hemophilia B gene therapy vector with a self-complementary vector genome and an expression cassette designed to express a codon-optimized FIX Padua transgene from the liver-specific transthyretin (TTR) promoter/enhancer combination." (PMID 32280725, 2020).
iron deficiency (4 papers, 2019 to 2025). "TTR serves as a sensitive marker of nutritional status, while transferrin levels correlate with iron deficiency, a common CD complication." (PMID 40325942, 2025).
ischemia (4 papers, 2019 to 2022). A hypoperfusion of the BLOOD through an organ or tissue caused by a PATHOLOGIC CONSTRICTION or obstruction of its BLOOD VESSELS, or an absence of BLOOD CIRCULATION. "In ischemia models, induced by permanent middle cerebral artery occlusion, TTR has been shown to be protective, as evidenced by the significant increase in cortical infarction, cerebral edema and the microglial-leukocyte response in mice with TTR deficiency compared with normal TTR levels." (PMID 34429155, 2021). "Growing evidence also suggests a wider role for TTR in CNS neuroprotection, including in ischemia, regeneration, and memory." (PMID 32197355, 2020). "A relationship between TTR and ischemia has also been established." (PMID 32197355, 2020).
Lewy body diseases (4 papers, 2014 to 2025). "TTR has been shown to facilitate in vitro proteolysis of specific conformations of misfolded α-synuclein into aggregation-incompetent fragments, suggesting that TTR has a direct neuroprotective role in Lewy body diseases." (PMID 40717228, 2025). "Ferritin and transthyretin CSF levels discriminated MSA patients from PD, progressive supranuclear palsy (PSP), and dementia with Lewy bodies (DLB)." (PMID 37426656, 2023). "CSF levels of transthyretin (TTR, a clearance protein produced in the choroid plexus) have been found to be increased in Lewy body diseases, including PD, PDD, and DLBD in relation with controls." (PMID 25426023, 2014).
liver cancer (4 papers, 2014 to 2025). An epithelial or non-epithelial malignant neoplasm that arises from the liver. "We revealed that high HHLA2 expression indicated worse outcome in early-stage of Barcelona Clinic Liver Cancer staging system (BCLC) (overall survival: P=0.0010; TTR: P=0.0044)." (PMID 35371079, 2022).
liver cirrhosis (4 papers, 2009 to 2024). "In multivariate analysis, γ-GT, tumor size, TNM stage and CCL24 level were associated with OS, whereas, γ-GT, liver cirrhosis, tumor number, microvascular invasion, BCLC stage and CCL24 level were associated with TTR." (PMID 28042950, 2017). "In univariate analysis, γ-GT, tumor number, tumor size, microvascular invasion, TNM stage, BCLC stage and CCL24 level were associated with OS, whereas, γ-GT, liver cirrhosis, tumor number, tumor size, microvascular invasion, TNM stage, BCLC stage and CCL24 level were associated with TTR." (PMID 28042950, 2017). "Meanwhile, serum AFP, whether there was liver cirrhosis, tumor size, and number of tumors were significantly correlated with TTR (serum AFP value = 0.044, P value for liver cirrhosis = 0.002, tumor size < 0.0001, tumor number < 0.0001)." (PMID 38500533, 2024). "Transthyretin is also considered a negative acute phase protein and is decreased in inflammation, malignancy, cirrhosis of the liver and protein wasting diseases due to reduced synthesis." (PMID 19424492, 2009).
liver fibrosis (4 papers, 2012 to 2023). "Liver fibrosis, indicated by collagen fibers and deposition by fibroblasts in the periportal region, was detected in 5 mice, and again, not in mice injected with the TTR-hFIX vector." (PMID 36507314, 2022).
metabolic syndrome (4 papers, 2018 to 2022). A cluster of metabolic risk factors for CARDIOVASCULAR DISEASES and TYPE 2 DIABETES MELLITUS. "Moreover, a relationship between RBP4, TTR and metabolic syndrome components was found in this study." (PMID 29747616, 2018). "Pearson correlation coefficients were used to assess the relationship between RBP4, TTR, and HOMA-IR, with metabolic syndrome parameters." (PMID 29747616, 2018).
nephrotic syndrome (4 papers, 2017 to 2025). A collection of symptoms that include severe edema, proteinuria, and hypoalbuminemia; it is indicative of renal dysfunction. "In the kidneys, TTR deposition may cause dysfunction of the lower urinary tract, nephrotic syndrome, and/or progressive renal failure." (PMID 40564893, 2025). "Patients with nephrotic syndromes have urinary losses of proteins that bind thyroid hormones, including thyroxine binding globulin, transthyretin, and albumin." (PMID 28117377, 2017).
orthostatic hypotension (4 papers, 2019 to 2025). Sudden fall of the blood pressure of at least 20/10 mm Hg when a person stands up. "The most frequent reason for prescribing TTR gene analysis was orthostatic hypotension (69%) while the most common reasons for not offering a TTR test were an alternative diagnosis (41%) or a lack of knowledge about the differential diagnosis of CIDP (41%)." (PMID 40025610, 2025).
renal dysfunction (4 papers, 2019 to 2024). "ROC analysis evidenced that combining RBP4 and TTR urine levels highly discriminated ADHF patients with renal dysfunction (AUC: 0.826, p < 0.001) and significantly predicted poor disease evolution over 18-month follow-up." (PMID 35216460, 2022). "For some treatments and pathological states, such as corticosteroid therapy, renal dysfunction, infection, physiological stress, and liver dysfunction, they can increase or decrease transthyretin levels." (PMID 31275452, 2019).
Sepsis (4 papers, 2019 to 2025). Sepsis is defined as life-threatening organ dysfunction caused by a dysregulated host response to infection. "Several proteins identified in this study, including Transthyretin (TTR) and C-reactive protein (CRP), have already been used to diagnose sepsis clinically." (PMID 31568522, 2019). "Indeed, TTR is a negative acute-phase protein, and patients with severe sepsis often have very low TTR concentrations." (PMID 35216460, 2022).
Anorexia (3 papers, 2016 to 2025). Lack of desire to eat (loss of appetite). "The high expression of TTR in the dorsomedial hypothalamus of rats with exercise-induced anorexia suggests that central TTR may also play a functional role in modulating food intake and energy balance." (PMID 31504048, 2019). "Gene expression profiling revealed an elevation of Ttr expression in the dorsomedial hypothalamus (DMH) of rats with exercise-induced anorexia, implying that central TTR may also play a functional role in modulating food intake and energy balance." (PMID 27053000, 2016). "Elevation of TTR in the DMH of rats with exercise-induced anorexia implies that DMH or central TTR may also play a functional role in modulating food intake and energy balance." (PMID 27053000, 2016).